IL6 (interleukin 6)
Diseases named in the same sentence as IL6 in open-access papers (continued):
Sharing a sentence is not in itself a finding about the gene and the disease.
asthma (continued). "In this experiment, IL-6 levels were upregulated in OVA-induced allergic asthma mice, indicating high levels and overactive Th2 cytokines, leading to airway hyperreactivity and asthma." (PMID 38731707, 2024). "IL-8 and IL-6, secreted by airway epithelial cells, are key drivers of non-T2 asthma, particularly through neutrophil recruitment, which contributes to steroid resistance." (PMID 39538061, 2024). "In addition to IL6R, we selected STAT3 for evaluation because IL-6/signal transducer and activator of transcription 3 (STAT3)-mediated signaling involved in various pathophysiological conditions including asthma and COPD." (PMID 38302925, 2024). "Klotho can also inhibit the nuclear translocation of NF-κB and the expression of downstream genes, reducing the release of inflammatory mediators such as interleukin-6 and tumor necrosis factor-alpha, thereby alleviating airway inflammation in COPD and asthma patients." (PMID 38287280, 2024). "IL-6 has not been demonstrated to be a useful biomarker for disease severity in a very large cohort of urban asthma patients." (PMID 38534377, 2024). "The evidence of MCs adjacent to blood vessels and the expression by MCs of some of the most important angiogenic factors (basic FGF and, VEGF, IL-6, and CXCL8) suggest that they may have a role in airway neovascularization in asthma." (PMID 37298721, 2023). "For patients with asthma, IL-6 has been found to have a negative correlation with FEV1.and is related to the loss of central airway function." (PMID 38093206, 2023). "There were unexpected relationships between IL-6 and S100B and white matter microstructure in those with asthma, but not controls." (PMID 37377978, 2023). "The same study reveals that IL-6 high subset of obese asthmatics suffering from other metabolic dysfunctions like hypertension has the highest incidence of asthma as compared with obese asthmatics without any metabolic dysfunctions." (PMID 37251328, 2023). "IL1ꞵ, IL-6, and TNF-α are also considered as major mediators of lung and airway inflammatory responses induced by allergen exposures in experimental and clinical cases of asthma." (PMID 37998734, 2023). "IL-6 levels can be used as an auxiliary indicator to distinguish individuals with asthma from healthy non-asthmatic controls." (PMID 37173781, 2023). "IL-6 levels are significantly elevated in pediatric patients with asthma (SMD 1.58, 95% CI 0.75–2.41, P = 0.0002) and mildly elevated in adult patients with asthma (SMD 1.08, 95% CI 0.27–1.90, P = 0.009)." (PMID 37173781, 2023). "Recent studies suggest that IL-6 plays an active role in the pathogenesis of COPD and asthma, and IL-6 could be a direct target in treatments of these and other chronic lung diseases." (PMID 38004123, 2023). "The level of IL-6 in the serum of patients with asthma is elevated; in a study of bronchoalveolar lavage fluid (BALF), IL-6 level in patients with active asthma was higher than that in healthy subjects and patients with stable asthma." (PMID 38093206, 2023). "Core target analysis showed that SZYQD may directly or indirectly affect asthma through potential targets, such as AKT, IL-6, TNF-α, and EGFR." (PMID 38093206, 2023). "Higher IL-6 levels are found in serum and sputum of asthma patients compared to non-asthmatic controls." (PMID 38062491, 2023). "We developed an IL-6 + sIL-6Rα gene signature and observed enrichment of this signature in bronchial biopsies but not nasal brushes from asthma patients compared to healthy controls." (PMID 38062491, 2023). "In search of novel approaches in diagnosing and treating patients with asthma, S100A12, ratio AGE/sRAGE, and DJ-1 in addition to IL-6 may prove to be useful tools." (PMID 37371535, 2023). "Similarly, fibroblast-derived IL6, IL8, and IL11 have been shown to activate and attract neutrophils during neutrophil inflammation in asthma but also to activate T-cells by increasing CD40L expression." (PMID 37497214, 2023).
asthma (continued). "The pooled SMDs revealed that serum IL-6 levels were significantly higher in the asthma group as compared to the healthy non-asthmatic controls group (SMD = 1.31, 95% CI: 0.82–1.81, P < 0.00001)." (PMID 37173781, 2023). "IL-6 and TNF-α are involved in the inflammatory reaction of asthma." (PMID 37492220, 2023). "Consequently, airway epithelium in patients with T2 asthma overproduces a broad pallet of pro-inflammatory cytokines and mediators including alarmins (IL-25, IL-33, TSLP), as well as IL-6, IL-8, IL-1α/β, RANTES, or TNF in response to environmental triggers." (PMID 37199256, 2023). "In addition, interleukins, especially IL6 and IL4, were suggested as prospective biomarkers of childhood asthma." (PMID 37241840, 2023). "Moreover, Th1 cells, Th17 cells, ILC1s, ILC3s, and M1 macrophages are involved in this endotype, and their production IL‐1β, IL‐6, IL‐17, IFN‐γ, and TNF‐α are responsible for the recruitment and activation of inflammatory cells during asthma attacks." (PMID 36051916, 2022). "Furthermore, it was found that the levels of TNF-α, IL-1β, IL-4, IL-5, and IL-13 in the BALF, and the levels of IL-17, IL-6, and OVA-specific IgE were observably increased in serum of RSV-infected asthma mice, while the level of IFN-γ was decreased." (PMID 36213326, 2022). "Cytokines, e.g. TNF, IL1β, IL5, IL6, IL12 and IL23, represent important therapeutic targets in immune-mediated inflammatory diseases (IMIDs), such as inflammatory bowel disease (IBD), psoriasis, asthma, rheumatoid and juvenile arthritis." (PMID 35731827, 2022). "Elevated levels of inflammation-related factors such as IL-6, C-reactive protein, and TNF-α are found in obese pregnant women, which may contribute to the development of wheezing and asthma in children." (PMID 37780583, 2022). "Administration of IL-6 inhibitor in mice with HDM-induced asthma did not result in reduced frequency of Th1-cells and IFNγ secretion and also the frequency and number of Th2-cells in the airways as compared to the saline control group." (PMID 35408882, 2022). "Obesity is well known to be a systemic, pro-inflammatory state, and there is evidence that some obese asthma is driven by systemically released IL-6 targeting the airways independent of immunoglobulin E (IgE) or blood eosinophil levels." (PMID 35722499, 2022). "In the same way as IL11 enhances the disease severity in asthma, overexpression of IL6 and IL11 in Asp may reflect the severity of IL6-mediated inflammation and type 2 inflammation enhancing the disease severity in CRS." (PMID 35628459, 2022). "The pro-inflammatory mediators IL-6, TNF-α, and CXCL8 consequently entail the infiltration of activated immune cells, such as mast cells, DCs, and lymphocytes, which are involved in the pathogenesis of asthma." (PMID 35743888, 2022). "They found that the best discriminants between asthma and controls were BAL IL-6 and IL-13." (PMID 35722499, 2022). "In conclusion, our study shows that bergenin regulates the NF-κB pathway and blocks p65 translocation into the nucleus by activating SIRT1, thereby reducing the release of proinflammatory factors (such as IL-1β, IL-5, IL-6, and MMP-9 by macrophages) to play a role in asthma treatment." (PMID 36313381, 2022). "Nevertheless, the efficacy of simultaneous pharmacological inhibition of TNF and IL-6 in asthma was not yet studied." (PMID 35408882, 2022). "In this study, we detected inflammatory cytokines in asthma patients with and without nocturnal symptoms and found that inflammatory factors, such as IL-6, were increased in the peripheral blood of patients with nocturnal asthma." (PMID 36505412, 2022). "However, we found that TNF-α and IL-6 in both asthma and COPD patients showed a tendency to decrease after administration of herbal medicines, and IgE in the asthma group showed a comparable decrease after 12 weeks." (PMID 35677382, 2022).
asthma (continued). "The OVA-induced asthma model with a circadian rhythm disorder and 16HBE cells treated with serum shock showed an increase in IL-6 levels and a negative correlation with BMAL1 and FOXA2." (PMID 36505412, 2022). "In a mouse obese asthma model, ILC3 stimulated by IL-1β, IL-6, or IL-23 produced IL-17A." (PMID 35626330, 2022). "IL-6-mediated JAK/STAT3 signaling plays a vital role in the airway remodeling of asthma, and its inhibition prevents airway inflammation and remodeling, and blocks Th2 and Th17 cell expansion in a murine asthma model." (PMID 35222040, 2022). "IL-6 was up-regulated in both ACO patients and ACO mice versus COPD or asthma." (PMID 35681424, 2022). "Expression of the cytokines TNF-α, IL-1β, IL-6, IL-5, and IL-8 were increased in placentae of female, but not male fetus, in pregnancies complicated by asthma." (PMID 36046194, 2022). "In T2 asthma, the Th2 cytokines IL-4, IL-5, IL-9, IL-13, and IL-25, and the acute proinflammatory cytokines TNF-α, IL-1β, IL-6, and IL-8, subsequently lead to bronchial hyperresponsiveness (BHR), and plasma cells and antibody-producing cells secrete antibodies." (PMID 36430662, 2022). "Interestingly, we found that most of the cytokines (IL-12p70, IL-13, IL-4, IL-6, TNF-α, and IL-8) in the asthma patients tend to increase when the low expression of eosinophils; but in the ACO group, only INF-γ and IL-10 showed an increase." (PMID 36311545, 2022). "Furthermore, the IL‐6 concentration in BALF was significantly increased by the same treatment, further confirming the establishment of the mouse model of OVA‐induced asthma." (PMID 34816611, 2022). "Macrophages isolated from patients with asthma generate more IL-6 than those in patients without asthma." (PMID 36499236, 2022). "In addition, the concentrations of IL-4, IL-5, and IL-13, as well as IL-1β, IL-6, and TNF-α, were greatly elevated in BALF and lung tissues, especially in lung tissues, of asthma mice, which were suppressed after the treatment of Ferr-1 and/or 3-MA." (PMID 35154576, 2022). "According to the prediction results of network pharmacology, IL-6, TNF, CXCL8, IL-10, IL-1β, and IL-4 may be the key targets of Danlong Dingchuan Decoction against asthma." (PMID 35186104, 2022). "Recent studies provide evidence that IL-6, rather than being involved in pneumonia, plays an important role in the pathogenesis of asthma." (PMID 35774748, 2022). "Unlike previous studies in adults, in children IL-6 showed lower blood levels, rarely above 3.1 pg/mL, and did not correlate with asthma severity." (PMID 33925009, 2021). "The inhibition of RORγt also attenuated the effects of anti-miRNA-221-5p on the increased levels of IL-6, IL-17, IL-21 and IL-22 levels, and inhibited levels of IL-10, IL-35 and TGF-β in in vitro model of asthma following anti-miRNA-221-5p, in comparison with anti-miRNA-221-5p group." (PMID 34863307, 2021). "Co-cultivation of epithelial cells with moDCs and/or moMφs without UPM did not change IL-6 or IL-8 protein secretion in the control, asthma, and COPD groups." (PMID 34168212, 2021). "IL-6 and TNF are the important inflammatory mediators in the pathogenesis of asthma." (PMID 34084159, 2021). "In the present study, we documented immunomodulatory mechanisms of GSYJ that relieve asthma symptoms, including AHR, lung inflammatory cell infiltration, and increased serum total IgE levels by regulating the expression of IL-5, IL-6, IFN-γ, IL-12, IL-1β, RANTES, and iNOS." (PMID 33708257, 2021). "Furthermore, the MAPK signaling pathway can control the expression of inflammatory factors (IL-6 and TNF-α) to regulate inflammation and immune responses in asthma." (PMID 34880921, 2021). "Furthermore, an increased anti-inflammatory effect of 1,25D3 was observed in BSMCs from COPD, for secreted IL-6 (954 ± 217-fold decrease, p < 0.001) and MCP-1 (488.9 ± 120-fold decrease, p < 0.01) than in BSMCs from asthma." (PMID 34512638, 2021).
asthma (continued). "With this objective they compared outcomes of metabolic dysfunction and asthma severity in IL-6-high and IL-6-low asthma, and stratified patients into obese and non-obese subgroups." (PMID 33418879, 2021). "Meanwhile, one novel study demonstrated that increased IL-6 is negatively correlated with a lower BOLD signal in caudate, supporting the hypothesis that inflammation in asthma may contribute to the functional changes in caudate." (PMID 33776882, 2021). "Moreover, the intensity of inflammation is higher in patients with obstructive lung diseases in our study, especially observed for IL-6 in COPD and IL-8 in both asthma and COPD, and include other mediators e.g., TSLP and IL-33 in asthma." (PMID 34168212, 2021). "Results showed adequate adherence was associated with lower levels of CRP, IL-6, and TNF-α, and soluble vascular cell adhesion molecule-1 (sVCAM-1) in healthy males and females, and IL-17 in both males and females with asthma." (PMID 34825233, 2021). "Patients with asthma who have high circulating concentrations of IL-6 have a much more severe asthma than those without predominant IL-6 inflammation." (PMID 33418879, 2021). "The inhibition of SOCS1 attenuated the effects of anti-miRNA-221-5p on the increased levels of IL-6, IL-17, IL-21 and IL-22, and suppressed levels of IL-10, IL-35 and TGF-β in in vitro model of asthma following anti-miRNA-221-5p, compared with anti-miRNA-221-5p group." (PMID 34863307, 2021). "In the inflammatory response, proinflammatory cytokines, such as IL-1β, IL-6, and TNF-α, activate the body's immune system and promote the aggregation and activation of inflammatory cells, which plays a crucial role in the process of asthma." (PMID 34966437, 2021). "The inhibition of FOXP3 attenuated the effects of miRNA-221-5p on the inhibition of IL-6, IL-17, IL-21 and IL-22 levels, and promotion of IL-10, IL-35 and TGF-β levels in in vitro model of asthma following anti-miRNA-221-5p, in comparison with anti-miRNA-221-5p group." (PMID 34863307, 2021). "Similar results were described in peripheral blood measurements, where neutrophil counts and IL-6 were significantly increased in the morbid obese adult asthma group compared with the non-obese group." (PMID 33418879, 2021). "Compared to the asthma and COPD groups, higher levels of IL-4, IL-6, TNF-α, IL-1β, IL-17A, and IFN-γ in ACO were observed, and there were significances in IL-4, IL-6, TNF-α, and IFN-γ compared to the control group (P < 0.01)." (PMID 33869177, 2021). "We found that moMφs without UPM treatment produced different cytokines in healthy people and patients with obstructive lung diseases—they do not produce IL-6 in asthma and COPD and secrete more IL-8 in COPD." (PMID 34168212, 2021). "Therefore, we measured IL-1β, IL-6, and TNF-α levels to indirectly verify the maturity of DCs in patients with asthma." (PMID 33503170, 2021). "Among them, the non-cytotoxic 2-aminobenzimidazole 49d was the most potent at inhibiting significantly: (i) MSK1 activity, (ii) the release of IL-6 in inflammatory conditions in vitro (IC50~2 μM) and (iii) the inflammatory cell recruitment to the airways in a mouse model of asthma." (PMID 33450992, 2021). "This flavonoid also inhibited the activation of NF-κB and STAT-1 in macrophages, and reduced inflammatory cytokines including; TNF-α, IL-6, IL-1β and PGE2 and also increased inflammatory cytokines in vitro, which it can useful for the treatment of allergic disorders such as asthma." (PMID 33295229, 2020). "For instance, IL-6 is increased in BALF and sputum of asthma patients." (PMID 33147273, 2020). "However, higher levels of IL-4, IL-17, IL-6, and IL-10 mRNA and lower levels of IFN-γ and TGF-β mRNA were observed in lungs of mice from the asthma group relative to those from the normal or PBS group." (PMID 32549755, 2020).
asthma (continued). "BAMBI knock out mice model of asthma demonstrated significantly reduced airway hyperresponsiveness, pulmonary inflammation, broncho-alveolar lavage fluid (BALF) eosinophil count, as well as diminished IL-4, IL-5, IL-13 and IL-6." (PMID 32900903, 2020). "For instance, a study investigating the anti-inflammatory effects of a drug called alloferon in OVA-induced asthma in mice has shown decreased levels of IL-5 and IL-6 production, as well as decreased OVA-specific IgG1 but not OVA-specific IgG2a." (PMID 32392269, 2020). "Indeed, IL-6 and CXCL8 are known to be increased in HBECs from asthmatics both under baseline conditions and after stimulation, suggesting a regulatory role for miRNAs in the control of IL-6 and CXCL8 expression in asthma." (PMID 33255348, 2020). "In the peripheral blood of children with asthma, the possibility of intestinal flora disorders and gastrointestinal discomfort symptoms increases, with the elevation in the levels of inflammatory factors such as TNF-α and IL-6." (PMID 33456673, 2020). "In accordance with our data, sIL-6R generation and therefore IL-6 trans-signaling in a murine model of acute experimental asthma was dependent on TLR2, but not TLR440." (PMID 31086276, 2019). "Higher levels of YKL-40 were associated with increased T1 inflammatory biomarkers such as IL-1β and IL-6, indicating that YKL-40 may be useful in predicting exacerbation rates and responses to asthma treatment regimens." (PMID 31113430, 2019). "For the epithelial environment stage of asthma (allergic sensitization stage), air exposure to allergens induces the secretion of proinflammatory cytokines (Group 1) in the airway epithelium, such as TSLP, IL-6, IL-8, TNF-α, IL-25, IL-33, and GM-CSF." (PMID 31284537, 2019). "The upregulated expression levels of IL-1β, IL-6, IL-12, IL-17A, KC, MCP-1 and TNF-α may contribute to airway neutrophilia and asthma exacerbation." (PMID 31889961, 2019). "In a Brazilian RCT10, a 12-week aerobic training program reduced both BHR and serum proinflammatory cytokines interleukin-6 (IL-6) and monocyte chemoattractant-1 (MCP-1), as well as reduced sputum eosonophils and fractional exhaled nitric oxide (FeNO) in asthma patients with more inflammation." (PMID 31427628, 2019). "As an important driver of inflammation in the bronchial epithelium, we showed that PAF stimulation increased the expression of IL-6, IL-1β, and TNF-α in HSAECs, and this effect was reduced by HSYA, thus potentially attenuating the secretion of inflammatory cytokines in asthma patients." (PMID 30123133, 2018). "Unlike beta-agonists (a conventional treatment in asthma), which can enhance IL-6 expression in the lung, NS had no, or only mild inhibitory effects on IL-1-induced IL-6 release." (PMID 30333747, 2018). "To specifically address the role of IL-6 produced by dendritic cells in allergic airway inflammation, we used mice with tissue-restricted inactivation of IL-6 in CD11c+ cells (CD11c-IL-6 KO) and subjected them, together with IL-6 KO mice and littermate WT control mice, to HDM-induced asthma model." (PMID 30534125, 2018). "In mice, anti-IL-6 therapy of high-dose HDM asthma is effective, but the contribution of IL-6 to a more clinically relevant low-dose HDM (10 μg) asthma model was not experimentally determined." (PMID 30534125, 2018). "The application of BET bromodomain mimics reduced in turn fetal calf serum plus transforming growth factor beta (TGF-β) -induced ASMC proliferation and interleukin 6 (IL-6) gene (IL6) and CXCL8 expression, with the required dose depending on asthma severity of cell donor." (PMID 29796022, 2018). "In addition to previously identified variables, the data provide further evidence for the importance of IL-2, IL-5, IL-6, IL-8, IL-10, IFN-γ, TNF, asthma, polyposis, and aspirin sensitivity, in efforts to demarcate distinct endotypes of CRS." (PMID 30283438, 2018).